NEAT1 (nuclear paraspeckle assembly transcript 1)
Synonyms: TncRNA; MENepsilon/beta; LINC00084; VINC; TP53LC15; NCRNA00084
Gene: Long non-coding RNA gene on chromosome 11 (65,422,774 to 65,445,540, forward strand). Ensembl gene ENSG00000245532.
Gene Ontology:
Biological process: miRNA-mediated post-transcriptional gene silencing
Cellular component: paraspeckles; RISC complex
Diseases named in the same sentence as NEAT1 in open-access papers:
NEAT1 is named in the same sentence as 355 diseases in open-access papers, as found by Europe PMC text mining. Sharing a sentence is not in itself a finding about the gene and the disease. The quoted sentences say what the papers report.
breast cancer (197 papers, 2015 to 2025). A primary or metastatic malignant neoplasm involving the breast. "Aberrant NEAT1 expression has been associated with poor prognosis and increased tumor aggressiveness in several cancers, including breast cancer, ovarian cancer, and glioblastoma." (PMID 40170567, 2025). "Cell cluster_5 is also significantly associated with lncRNA-Topic 13, which includes MALAT1 and NEAT1 as top ranked genes, two lncRNAs extensively studied in breast cancer progression." (PMID 38611028, 2024). "Some of the well-studied lncRNAs such as MALAT1 and NEAT1 are known for their causal impact on breast cancer metastasis." (PMID 38838009, 2024). "NEAT1, has been detected in the exosomes of breast cancer patients, showing an association with clinical parameters, particularly metastasis and chemoresistance, is of great interest." (PMID 38612643, 2024). "Elevated NEAT1 expression in tumor tissues is associated with poor survival in breast cancer patients." (PMID 37583933, 2023). "Out of the 13 available survival curve results, low expression of NEAT1 or high expression of SNHG16 was associated with significantly shorter survival in 626 breast cancer patients." (PMID 33494814, 2021). "The lncRNA nuclear paraspeckle assembly transcript 1 (NEAT1) has been identified in several human cancers and has been intimately linked to breast cancer progression by stimulating cell proliferation, EMT, and metastasis." (PMID 32244924, 2020). "In conclusion, NEAT1-caused down-regulation of miR-133b promotes breast cancer metastasis through up-regulating TIMM17A, a target of miR-133b." (PMID 31344855, 2019). "To test the effect of Neat1 knockdown on Brca1-deficient mammary tumor development, we perform in vivo tumorigenicity analysis on scramble (as a control) and Neat1 shRNA transfectants of primary tumor cell cultures." (PMID 27556296, 2016). "Neat1 knockdown by two different Neat1 shRNAs significantly impaired the development of Brca1-deficient xenograft mammary tumors." (PMID 27556296, 2016). "Among the identified lncRNAs, serum NEAT1 has been shown to be promising diagnostic and prognostic biomarkers for other types of cancer including colorectal cancer, hepatocellular carcinoma and breast cancer." (PMID 40259205, 2025). "For instance, the hypoxia-induced Nuclear-Enriched Abundant Transcript 1 (NEAT1) lncRNA has been associated with the formation of nuclear structures called paraspeckles during hypoxia as well as an increased clonogenic survival of breast cancer cells." (PMID 38501112, 2024). "Notably, serum expression level of NEAT1 has shown acceptable diagnostic power in differentiation of breast cancer patients from healthy individuals with an area under curve (AUC) value of 0.83 (CI = 0.73 to 0.93, p < 0.0001)." (PMID 37310654, 2023). "Furthermore, lncRNA Neat1 is a novel cancer-associated lncRNA that is highly expressed in various cancers and plays a major role in breast cancer proliferation, invasion, and metastasis." (PMID 37204526, 2023). "Differential RNAP of NEAT1 has important biological consequences, as higher expression of a longer isoform of NEAT1 has been associated with poor prognosis in breast cancer, though the mechanism remains unknown." (PMID 36284317, 2022). "Importantly, HMGA2 is implicated in regulating breast cancer cell growth, invasion and 5-FU resistance mediated via nuclear paraspeckle assembly transcript 1 (NEAT1)." (PMID 34281530, 2021).
breast cancer (continued). "In breast cancer for example, lncRNAs nuclear paraspeckle assembly transcript 1 (NEAT1), metastasis-associated lung adenocarcinoma transcript 1 (MALAT1), and non-coding RNA in the aldehyde dehydrogenase 1A pathway (NRAD1), have all been described as oncogenic and dysregulated in breast cancer." (PMID 34072264, 2021). "NEAT1 was identified as one out of three genes with recurrent mutations in breast cancer." (PMID 33329688, 2020). "Similarly, lncRNA NEAT1 is expressed at significantly high levels in tissues and cell lines of breast cancer, and its knockdown caused a decrease in cell proliferation and EZH2 expression." (PMID 32157157, 2020). "Interestingly, three out of four identified promoter mutations interfered with NEAT1 expression, in line with its frequent focal deletion in breast cancers." (PMID 33329688, 2020). "In addition, focal deletions within the NEAT1 gene were found in 8% of breast cancers, and mutations are frequently found in the exonic region." (PMID 31992741, 2020). "To validate whether NEAT1 is associated with the down-regulation of miR-133b in breast cancer cells, we first identified specific interactions between NEAT1 and miR-133b by luciferase reporter assay." (PMID 31344855, 2019). "In addition, deep sequencing analysis of breast cancers has indicated mutations in the NEAT1 promoter region." (PMID 30374364, 2018). "However, hypoxic induction of NEAT1 promotes cell proliferation and survival and inhibits apoptosis, while high expression of NEAT1 in breast cancer is associated with a poor prognosis." (PMID 26590207, 2016). "Finally, we show that hypoxia-induced NEAT1 accelerates tumor cell proliferation and inhibits apoptosis and that high levels of tumor NEAT1 are associated with adverse clinical outcome in breast cancer." (PMID 25417700, 2015). "Moreover, NEAT1 is crucial for tumorigenicity of BRCA1-deficient breast cancer." (PMID 27556296, 2016). "The short isoform of NEAT1 (NEAT1_1) plays a crucial role in promoting aerobic glycolysis in breast cancer." (PMID 40804479, 2025). "The present study revealed a notable reduction in serum NEAT1 expression among breast cancer patients when compared to individuals with fibromas and control subjects." (PMID 40149989, 2025). "Elevated levels of NEAT1 in breast cancer enhance glycolysis by scaffolding key glycolytic enzymes, including PGK1, PGAM1, and ENO1, concurrently within the same cellular context, thereby promoting breast cancer progression and metabolism." (PMID 40711448, 2025). "Similar to NEAT1 in breast cancer, the c-Myc-responsive lncRNA glycoLINC (gLINC) promotes glycolysis by acting as a scaffold for glycolytic enzymes, including PGK1, ENO1, PKM2, and LDHA, with indirect binding to PGAM1." (PMID 40804479, 2025). "In the cytoplasm, Pinin mediates the glucose-stimulated nuclear export of the lncRNA NEAT1 to promote breast cancer growth and metastasis by regulating glycolysis." (PMID 40221424, 2025). "The level of NEAT1-2 is notably correlated with HER2 in samples of breast cancer and with the grade of breast cancer." (PMID 41244835, 2025). "For instance, NEAT1 promotes breast cancer progression by forms a scaffold bridge for the assembly of PGK1/PGAM1/ENO1 complexes, yet other studies describe tumor-suppressive functions of NEAT1 in different contexts." (PMID 41361062, 2025). "Although research on the role of AUF1 in glucose metabolism is limited, a recent study has underscored the functional role of NEAT1 in glycolysis related to breast cancer progression." (PMID 40711448, 2025). "Consistently, mammary tumor weight and size were reduced in Neat1−/− mice compared with Neat1+/+ mice crossed with MMTV-PyVT transgenic mice." (PMID 40804479, 2025). "NEAT1 is also reported to negatively regulate miR-218, leading to enhanced breast cancer cell invasion." (PMID 39912983, 2025).
breast cancer (continued). "The knockdown of NEAT1, a long noncoding RNA, inhibited cell growth and induced cell apoptosis in breast cancer cells; miR-548ar overexpression downregulated NEAT1 expression and promoted apoptosis." (PMID 40345591, 2025). "High expression of ALYREF was found to selectively regulate the short isoform of nuclear paraspeckle assembly transcript 1 (NEAT1) to impact energy metabolism and promote tumour growth in breast cancer." (PMID 39915011, 2025). "For example, NQO1 [NAD(P)H: quinone oxidoreductase 1] expression in radiation-resistant breast cancer cells, had been positively regulated by lncRNA NEAT1." (PMID 39912983, 2025). "LncRNA NEAT1 levels decreased, and the ability of NEAT1 to differentiate breast cancer patients was confirmed by multivariate analysis and ROC method." (PMID 38956558, 2024). "The targeting of miR-146b-5p in breast cancer tissues and cell lines has also been implicated in the role of NEAT1 in EMT, progression and survival in breast cancer." (PMID 39272915, 2024). "We also expanded our analysis to include breast cancer cell lines with varied A3B expression and minimal A3A interference, and quantified C > U editing of DVRs within NEAT1 and MALAT1, the two transcripts with highest degree of C > U editing, using ddPCR." (PMID 39322638, 2024). "Specifically, HOTAIR and NEAT1 demonstrated feasibility in differentiating between breast cancer and fibroadenoma." (PMID 38505593, 2024). "Annotated lncRNAs already implicated in breast cancer (DSCAM-AS1, NEAT1, SNHG3, ZFAS1) also had a significant (FDR ≤ 0.3) effect, indicating the screen was able to identify functional lncRNAs." (PMID 38745269, 2024). "Modulation of miR-448 and resulting upregulation of ZEB1 have been identified as mechanisms of NEAT1-promoted breast cancer progression." (PMID 39272915, 2024). "NEAT1 (Nuclear Enriched Abundant Transcript 1) is a well-known conserved lncRNA that plays an important role in the development of several cancers, including lung cancer, breast cancer, and prostate cancer." (PMID 39036601, 2024). "Aberrant expression of NEAT1 in serum samples of breast cancer patients is correlated with clinicopathological characteristics, including pathological types, tumor size, histological grading, TNM stage, and hormonal status." (PMID 37310654, 2023). "NEAT1 knockdown increased miR-107 expression, and suppressed cell proliferation, migration, and invasion in breast cancer cells." (PMID 37310654, 2023). "ALYREF activates the expression of lncRNA NEAT1 and selectively upregulates the short isoform at the post‐transcriptional level, which promotes breast cancer cell metabolism and progression." (PMID 37537569, 2023). "Mechanistically, we reveal that VIRMA overexpression upregulates the m6A-modified long non-coding RNA, NEAT1, which contributes to breast cancer cell growth." (PMID 37208522, 2023). "The overexpression of NEAT1 plays a crucial oncogenic role in other solid tumors, such as lung cancer and breast cancer." (PMID 37835380, 2023). "The most notable of these lncRNAs is NEAT1, which has been reported to confer oncogenic potential in breast cancer." (PMID 37208522, 2023). "In this study, NEAT1 is highlighted as a significant contributor to breast cancer development, particularly in the TNBC subtype." (PMID 37958880, 2023). "The Kaplan–Meier curve revealed that breast cancer patients with high expression levels of NEAT1, miR‐21, and ribonucleotide reductase regulatory subunit M2 (RRM2) had a worse prognosis compared with those with low levels." (PMID 37310654, 2023). "The main mechanism of LncRNAs is through the competitive binding mechanism of miRNAs, and LncRNA H19/miR-675 and LncRNA NEAT1/miR-204 have been reported to interact in a competitive binding manner in breast cancer." (PMID 37280692, 2023).
breast cancer (continued). "For example, PCA3 (prostate cancer antigen 3, lncRNA) is considered a biomarker in prostate cancer, and the high expression of lncRNAs CCAT2, MALAT1, and NEAT1 is related to worse OS in breast cancer." (PMID 36924407, 2023). "In gastric cancer, for instance, researchers found that silence of lncRNA NEAT1 inhibits malignant biological behaviors and therapy resistance.In breast cancer, the down-regulation of NEAT1 increased cancer cells chemo-sensitivity." (PMID 37407915, 2023). "Previous studies have also shown that circ-NOTCH3 and the long non-coding RNA NEAT1 can promote breast cancer development by up-regulating KLF12 expression." (PMID 37156774, 2023). "NEAT1 was shown to enhance the proliferation, migration, and invasion, and promote the chemoresistance of MCF-7 and MDA-MB-231 breast cancer cells to cisplatin, paclitaxel, and 5-fluorouracil in vitro, while NEAT1 silencing reversed these effects." (PMID 37310654, 2023). "Breast cancer with lymph node metastases were in general associated with lower levels of the CSC genes ALDH1A3 and CD44, pluripotency markers POU5F1 and NEAT1, EMT marker SLUG, and drug resistance associated gene ERBB2, after DOX treatment." (PMID 38124067, 2023). "Several studies have shown that lncRNAs LINC01605, LINC00926, LINC00538 (YIYA), and lncRNA Neat1 are closely related to the level of glycolytic enzymes in breast cancer." (PMID 37204526, 2023). "A study suggested that serum levels of NEAT1 along with lncRNA H19 were upregulated in plasma samples of breast cancer patients compared with healthy women." (PMID 37310654, 2023). "The results showed increased expression of NEAT1 versus downregulated miR-107 in breast cancer cells." (PMID 37310654, 2023). "Zinc finger protein X-linked (ZFX) was identified as a target gene of miR-138-5p, which can be overexpressed by NEAT1 in breast cancer cells." (PMID 37310654, 2023). "miR-107 was shown to negatively regulate NEAT1 expression and regulate breast cancer progression through affecting the tumor development-associated genes, including TIMP-1, PDGF-A, SERPINB2, cyclin D1, CDK4, and CPA1A in breast cancer cells." (PMID 37310654, 2023). "miR-101 is a target of NEAT1 in breast cancer cells and Enhancer of Zeste 2 Polycomb Repressive Complex 2 Subunit (EZH2) was identified as a downstream target of miR-101." (PMID 37310654, 2023). "TCGA data analysis revealed that the expression level of lncRNA NEAT1 has a significant up-regulation in high-throughput Breast cancer samples compared to control samples (logFC: 8.906262, adj." (PMID 35581633, 2022). "It has been reported that Lnc NEAT1 regulated the occurrence of hemangiomas and promoted breast cancer cell survival." (PMID 35850692, 2022). "This integrated computational and experimental investigation revealed some new aspects of the lncRNA NEAT1 as a potential prognostic biomarker for the breast cancer and gastric cancer samples." (PMID 35581633, 2022). "Recently, accumulating evidence suggests that NEAT1 acts as tumor-promoting in the occurrence and development of most tumors, such as breast cancer, multiple myeloma, and pancreatic cancer." (PMID 35237319, 2022). "For example, NEAT1, a hypoxia-induced nuclear lncRNA, played a pro-tumorigenic role in breast cancer by accelerating cell proliferation and reducing apoptosis." (PMID 36127332, 2022). "GEPIA2 online data analysis revealed that NEAT1 had a significant downregulation in the breast cancer and gastric cancer samples." (PMID 35581633, 2022). "High expression of lncRNA NEAT1 predicted poor overall survival in breast cancer patients, and silencing of lncRNA NEAT1 suppressed the EMT process through upregulation of miR-146b-5p." (PMID 36685962, 2022).